E2F1 (E2F transcription factor 1)
Diseases named in the same sentence as E2F1 in open-access papers (continued):
Sharing a sentence is not in itself a finding about the gene and the disease.
breast carcinoma (continued). "For example, in breast cancer, miR-17-5p represses the expression of the nuclear receptor coactivator amplified in breast cancer 1 (AIB1) that enhances the transcription activity of E2F1 to promote the cell proliferation of breast cancer cells." (PMID 25302307, 2014). "Since KDM2A could bind to E2F1, transient transfection experiments were conducted in MCF7 breast cancer cells to assess whether KDM2A had an effect on the transcriptional activity of E2F1." (PMID 25029110, 2014). "Because TMCG/DIPY treatment modulates the methylation status and stability of E2F1, we observed that the 4OHT-dependent overexpression of E2F1 positively influences E2F1-mediated cell death in ERα-negative breast cancer cells." (PMID 25064027, 2014). "In addition, integrating pathway and gene information, we identified five (ID4, ANXA4, CXCL9, MYLK, FBXL7) and six (SQLE, E2F1, PTTG1, TSTA3, BUB1B, MAD2L1) known cancer genes significant for ovarian and breast cancer respectively." (PMID 22759382, 2012). "The results agree with those obtained by shRNA-mediated silencing of E2F1 and indicate that TMCG/DIPY may induce E2F1-mediated apoptosis in breast cancer cells." (PMID 23251702, 2012). "We further verified E2F1 as a key factor in activating h-eag1 transcription: E2F1-dODN decreased h-eag1 mRNA level by ∼80% in SHSY5Y human neuroblastoma cells and MCF-1 human breast cancer cells." (PMID 21655246, 2011). "Other known breast cancer gene target such as ERBB2, E2F1 and MTDH are in the global driver list." (PMID 21806811, 2011). "The obtained data indicated that antimitotic effect of D-glucuronyl C5-epimerase in human breast cancer cells in vitro probably is realized mainly via the activation of tumour suppressor genes р53, BRCA1, SYK and E2F1 and change of a balance of pro- and anti-apoptotic factors BCL2, NFKB1 and TNF." (PMID 20723247, 2010). "In summary, the obtained results showed that D-glucuronyl C5-epimerase significantly suppress proliferative activity of breast cancer cells in vitro through the activation of tumour suppressor genes р53, BRCA1, SYK and E2F1 and change of a balance of pro- and apoptotic factors BCL2, NFKB1 and TNF." (PMID 20723247, 2010). "E2F1 directly stimulated protease, serine S1 family member 22 (PRSS22) transcription, which facilitated efficient cleavage of Annexin A1 (ANXA1), producing an N-terminal peptide to activate formyl-peptide receptor-2 (FPR2)/ERK cascade, thus favoring the invasive phenotype in breast cancer." (PMID 39119602, 2024). "A previous study indicated that ANKRD22 could serve as a transcription factor and activate the expression of E2F1 in lung cancer progression, which suggests that ANKRD22 might regulate other factors to affect breast cancer development and this needs further investigation." (PMID 32651974, 2021). "However, E2F1 fails to upregulate ESRP1 despite its abundance in oxygen-deprived breast cancer cells." (PMID 34362878, 2021). "Indeed, our data showed that co-expression of miR-125a and miR-205 was more potent than either miRNA alone to inhibit erbB3 expression, decrease the levels of p-HER3, p-Src, p-Akt, and E2F1, and induce expression of p27kip1 in HER2-overexpressing breast cancer cells." (PMID 30093840, 2018). "Since the GDS3283 is a breast cancer data set, we selected the ChIP-seq experiments from breast cancer cell lines (T47D and MCF7 cells) to generate the regulatory TF network with Q < 0.001, which contained five significant TFs: ESR1, GATA3, FOXA1, MYC and E2F1." (PMID 24302579, 2014). "Interestingly, our study identified a potentially novel functional relationship between E2F1 and KIAA0191, which may be of clinical relevance to breast cancer patients." (PMID 21453498, 2011). "Although these studies were not performed using breast cancer samples, several predicted links between genes and regulators were substantiated by these experimental data (solid arrows stemming from Myc and E2F1)." (PMID 16670008, 2006).
breast carcinoma (continued). "Moreover, there were higher observed co-expression scores for FOXM1/E2F1, FOXA1/GRHL2, FOXA1/GATA3, suggesting that absence of FOXA1 might contribute to doxorubicin resistance in breast cancer cells through collaboration with the down-regulated GRHL2 and/or GATA3." (PMID 34395436, 2021). "Using a Fisher’s exact test, we observed that the distribution of direct E2F1 targets was significantly higher in the genes concordant with human breast cancer metastasis predictions (p = 0.001) than genes either discordant or not predictive of human breast cancer metastasis." (PMID 31341204, 2019). "Compared to normal tissue controls, however, the relocation of E2F7, but not E2F1, from the nucleus to the cytoplasm is induced by the overexpressed XPO1, and is commonly observed in colorectal cancer, prostate cancer, breast cancer, and HNSCC." (PMID 35197448, 2022). "Intriguingly, among cancerous cells, the E2F1 ChIP signal was present for some cells (melanoma, myeloma, and MDA-MB-231 breast cancer cells), but not for others (HeLa, Burkitt lymphoma, MCF7 and K562)." (PMID 36231008, 2022). "Previously, we demonstrated that silencing E2F1 or E2F3 suppresses centrosome amplification (CA) and chromosome instability (CIN) in Her2+ breast cancer cells without markedly altering proliferation." (PMID 26512919, 2015). "In this cohort, more than half of HR(+)/HER2(−) and breast cancer tissues were negative for both HOXB9 and E2F1." (PMID 25136922, 2014). "We observed that by modulating the posttranslational state of E2F1, the TMCG/DIPY combination was more active in the presence of 4OHT in an ERα-negative breast cancer model." (PMID 25064027, 2014). "Similarly to the patterns of expression of mitotic kinases in breast cancers that do not fall under traditional classification (or that failed to classify) FOXM1, E2F1, E2F2, E2F3, and c-Myc are overexpressed in that subtype." (PMID 36494865, 2022). "E2F1 and E2F3 are oncogenes and have negative correlations with breast cancer patient survival." (PMID 36424626, 2022). "Interestingly, other study showed a negative correlation between E2F1 and SETD7 in vivo and in clinical specimens: Overexpression of E2F1 leads to SETD7 downregulation and EGFR and Snail upregulation in breast cancer cells." (PMID 35812730, 2022). "Moreover, E2F1-5, but not E2F6 or E2F7, are elevated and correlate with a higher proliferation index and a poorer clinical outcome in breast cancer." (PMID 26992224, 2016). "More than half of HR(+)/HER2(−) breast cancer tissues were negative for both HOXB9 and E2F1." (PMID 25136922, 2014). "The lack of correlation between TFDP1 and E2F1 expression suggests that TFDP1 may have a function in addition to gene transcription regulation and cell cycle progression in breast cancer." (PMID 19995430, 2009).
prostate carcinoma (136 papers, 2009 to 2026). A carcinoma that arises from epithelial cells of the prostate gland. "The RB1/E2F1 axis is closely associated with prostate cancer neuroendocrine differentiation, and its dysregulation is linked to uncontrolled cell cycle progression during cancer development." (PMID 41492471, 2026). "A previous study has reported that increasing E2F1 expression levels are associated with tumor growth and cell survival rate of prostate cancer." (PMID 41540805, 2026). "Aberrant activation of E2F Transcription Factor 1 (E2F1) in tumors has been associated with a poor prognosis, which has also been established in prostate cancer." (PMID 38374143, 2024). "For instance, PPP1R14C, an E2F1 target, which encodes a regulatory inhibitor subunit of protein phosphatase 1 and promotes cell-cycle progression and migration in prostate cancer cells, was specifically activated by the K450/451R mutant." (PMID 37663929, 2023). "The resultant synergistic effects of MYC/E2F1/TERT expression with the rs2853669 polymorphism further deteriorated the prognosis of prostate cancer." (PMID 37174115, 2023). "In prostate cancer, loss of the tumour suppressor gene, Retinoblastoma (Rb), and consequent activation of transcription factor E2F1 typically occurs at a late-stage of tumour progression." (PMID 37363926, 2023). "Rb loss and E2F1 activation increase AR levels in prostate cancer and are associated with CRPC, in which the AR can promote cell growth and proliferation in a hormone-independent fashion." (PMID 37363926, 2023). "Given that prostate cancer is a highly heterogeneous tumor, somatic mutations of clinicopathologically significant E2Fs, including the E2F1, E2F2, E2F3, E2F5, and E2F6, were further investigated in PCa patients." (PMID 35531101, 2022). "In this study, we used PCA to distinguish the main factor among EZH2, TROAP and E2F1 causing tumorigenesis and development of prostate cancer." (PMID 33692939, 2020). "We found a relatively high rate of genomic amplification or mutation of E2F1 in several types of cancers, including prostate cancer." (PMID 32354165, 2020). "Taken together, these findings suggest that deregulation of the MYC/E2F1/RB1 cell-cycle regulator axis by various means is a ubiquitous event in AR indifferent prostate cancer that is necessary to overcome the G1 arrest caused by low AR activity." (PMID 31551480, 2019). "Together, these data indicate that GDNF stimulation is associated with reduced RB activity and enhanced E2F1 and AR target gene expression in a subset of prostate carcinoma that are receptive to GDNF signaling by virtue of RET and/or GFRA1 receptor expression." (PMID 25575823, 2015). "E2F1 is a direct activator of the AR promoter, and loss of RB is associated with increased AR levels and progression of prostate cancers to castration resistance." (PMID 23902736, 2013). "Additionally, we identified five downstream genes (IGF1R, BMI1, RHAMM, NuSAP1, and PBK) of E2F1 in prostate cancer, and these genes are associated with the survival and proliferation of prostate cancer." (PMID 38374143, 2024). "Furthermore, targeted knockdown of E2F1 enhances the susceptibility of tumor cells to ICAM-1-mediated anti-tumor immunity against prostate cancer." (PMID 24742333, 2014). "Evaluation of VCaP prostate cancer cell line–derived mouse xenograft tumors after 5 days of NXP800 treatment by RNA-seq demonstrated significant de-enrichment of Hallmark E2F Targets together with significantly decreased “activating” E2F (E2F1–3) RNA levels when compared with vehicle controls." (PMID 39787247, 2025). "Furthermore, knockdown of E2F1 inhibited tumor growth of prostate cancer in vivo through increasing the susceptibility of tumor cells to ICAM-1-mediated anti-tumor immunity including enhancement of monocyte adhesion, leucocytes infiltration, as well as cytotoxicity against tumor cells." (PMID 24742333, 2014).
prostate carcinoma (continued). "Further peak visualization of ChIP-sequencing data in both prostate cancer cell LNCaP and abl showed significant binding enrichment of E2F1 within the promoters of CDRs, which was further validated with ChIP-qPCR experiments in prostate cancer cells." (PMID 41492471, 2026). "Chromatin immunoprecipitation (ChIP) data confirm that SETD6 impacts the binding of E2F1 and BRD4 at the same target loci, establishing a novel mechanism by which SETD6 methylation of E2F1 modulates gene regulation programs in prostate cancer cells." (PMID 41540805, 2026). "In combined ChIP-seq and RNA-seq experiments, we observed differential transcriptional regulation in WT SETD6 WT or SETD6 KO prostate cancer cells expressing Flag-E2F1." (PMID 41540805, 2026). "Collectively, these results demonstrate that the RB1/E2F1 axis mediates the enhanced expression of CDRs in advanced prostate cancer." (PMID 41492471, 2026). "Further mechanistic studies revealed that CDC20, DTL, and RRM2 were transcriptionally regulated by the RB1/E2F1 axis, mediating cell cycle progression in prostate cancer." (PMID 41492471, 2026). "In our previous study, we described that SETD6 methylates E2F1 at K117 in vitro and in prostate cancer cells." (PMID 41540805, 2026). "In this study, the role of SETD6 mediated K117 monomethylation of E2F1 was investigated in prostate cancer cells." (PMID 41540805, 2026). "Further, additional studies are needed to understand the biological importance of this positive-feedback loop in prostate cancer as well as other cancer cell models that demonstrate a positive correlation between E2F1 and SETD6 gene expression levels." (PMID 40102573, 2025). "While investigating the high expression level of SETD6 in prostate cancer, Kublanovsky and colleagues discovered that E2F1 occupies the SETD6 promoter and upregulates SETD6 mRNA expression." (PMID 40102573, 2025). "The E2F1 transcription factor plays a pivotal role in promoting the proliferation of both SCs and prostate cancer cells by regulating cell cycle gene expression." (PMID 40869329, 2025). "To understand the mechanism regulating HSPB6 expression in prostate cancer, we performed a series of bioinformatics analyses and identified E2F1 as the only factor with a clear correlation with HSPB6." (PMID 38374143, 2024). "As such, POM121 promoted lethal prostate cancer through binding to importin-β, leading to nuclear import of oncogenic transcription factors (E2F1, MYC e.a.)." (PMID 38177114, 2024). "This novel compound has demonstrated comparable stability and heightened efficacy for eliminating lung cancer and prostate cancer cells, positioning it as a potent candidate for developing targeted therapy against E2F1-induced tumors." (PMID 39119602, 2024). "Another report found that crocin suppresses the re-proliferation of quiescent prostate cancer cells in vitro via down-regulation of important regulatory transcription factors such as Skp2, E2F1, NF-kB, C-myc, and other cell-cycle-regulatory genes." (PMID 38201944, 2023). "E2F1 is a potent oncogene in human cancers, including thyroid cancer, prostate cancer, lung cancer, and colorectal cancer, that can accelerate the invasion, spread, and metastasis of cancer cells and further predict poor prognosis." (PMID 37063290, 2023). "Co-deletion of RB1 and RNASEH2B was associated with PARPi resistance in prostate cancer cell lines due in part to E2F1-induced BRCA2 expression, however, inhibition of ATR was able to overcome this resistance via disruption of E2F1-induced BRCA2 expression." (PMID 37430137, 2023). "In contrast, in other cancers, such as prostate cancer, E2F-1 is considered to be a tumor suppressor by inducing apoptosis, thus establishing the dual function of E2F-1 in tumor progression." (PMID 36766831, 2023).
prostate carcinoma (continued). "He found that DU145 prostate carcinoma cells treated with lovastatin expressed less E2F-1 transcription factor, resulting in increased apoptosis and a reduction of the number of cells in the S-phase of the cell cycle." (PMID 36127484, 2023). "In prostate cancer specifically, E2F1 was shown to act in a dichotomic manner in several oncogenic processes." (PMID 37690684, 2023). "In prostate cancer cell lines, the combination was shown to suppress the p-Rb1-E2F1 signalling axis leading to inhibition of E2F1 gene targets such as BRCA1/2 and RAD51 among others." (PMID 37430137, 2023). "The E2F1-mediated upregulation of Rad51 contributes to the chemoresistance of prostate cancer cells under hypoxic conditions." (PMID 36833320, 2023). "In early prostate cancer, Rb tightly regulates E2F1, which in addition to acting on CycE, also controls the expression levels of AR, therefore linking Rb/E2F and AR signalling." (PMID 37363926, 2023). "Our latest study also identified the interaction between NCAPD3 and E2F1 in prostate cancer which increased the binding of E2F1 to the promoter of EZH2." (PMID 35689245, 2022). "E2F1 has been attributed to numerous cancer hallmarks in prostate cancer, including cell cycle, proliferation and apoptosis, and its expression is so closely aligned with disease stage that it has been proposed as a potential biomarker." (PMID 35406480, 2022). "Avasimibe also suppresses tumor proliferation and metastasis via the E2F-1 signaling pathway and has potential utility in treating prostate cancer." (PMID 35335693, 2022). "In bladder and prostate cancer cell lines, E2F1 enhanced cancer cell glycolysis by directly binding to the proximal SIRT6 promoter and suppressed SIRT6 expression, as well as significantly enhanced glucose uptake and lactate production." (PMID 35689245, 2022). "Based on the significant prognostic value of E2F1 and E2F6 as well as their association with tumor stage and Gleason score in prostate cancer, we generated nomograms for predicting a patient’s 1-year, 3-year and 5-year relapse-free survival." (PMID 35531101, 2022). "E2F1 is regulated by miR-20a, miR-106b, and miR-330 in prostate cancer and affects cell epigenetic changes related to cell growth (resistance to apoptosis)." (PMID 35123404, 2022). "E2F1/E2F2 expression correlates with malignancy in prostate cancer (PCa), but its functional significance remains unresolved." (PMID 36230876, 2022). "The findings suggest that VA acts as a HDAC3 inhibitor with anti-cancer effect on prostate cancer by regulating E2F1/E2F3/CASP3 axis." (PMID 36175803, 2022). "We found that E2F target genes involved in nucleotide biosynthesis contribute to maintaining genome stability in prostate cancer cells, but their enzymatic activity is insufficient to prevent replication stress after E2F1/E2F2 depletion." (PMID 36230876, 2022). "GAS5 interacts with E2F1 (E2F Transcription Factor 1) and enhances its binding to the P27Kip1 promoter, which leads to cell cycle arrest in prostate cancer." (PMID 34202777, 2021). "The aberrant activation of E2F1 also participated in the cellular proliferation, differentiation and apoptosis of colon cancer and prostate cancer and is often related to a poor prognosis." (PMID 34068010, 2021). "Recent studies have shown that E2F1 is highly expressed in prostate cancer cells as an oncogene, and its expression level is closely related to the occurrence, development, and poor clinical prognosis of prostate cancer." (PMID 34926692, 2021). "Correspondingly, the E2F1-p73-apoptosis axis was reported to be involved in p27T187A knock-in-mediated regulation of advanced prostate cancer." (PMID 34564711, 2021).